CCL19 (C-C motif chemokine ligand 19)
Diseases named in the same sentence as CCL19 in open-access papers (continued):
Sharing a sentence is not in itself a finding about the gene and the disease.
pneumonia (2 papers, 2023 to 2025). An acute, acute and chronic, or chronic inflammation focally or diffusely affecting the lung parenchyma, caused by an infection in one or both of the lungs (by bacteria, viruses, fungi, or mycoplasma.). "When Staphylococcus aureus is given to mice with pneumonia, enterotoxin B is released, which raises Ccl19 levels in lungs and worsens lung inflammation." (PMID 37362920, 2023). "Collectively, the therapeutic effects of QKL treatment on alleviating pneumonia may be dependent on suppression of the NF-κB pathway, reduction of gene (Ccl19 and Ccl21) expression and Staphylococcus abundance." (PMID 37362920, 2023). "In the study, the abundance of Staphylococcus rose, which might upregulate Ccl19 expression and exacerbate pneumonia, and QKL reversed these effects." (PMID 37362920, 2023).
polyp (2 papers, 2011 to 2024). A usually exophytic mass attached to the underlying tissue by a broad base or a thin stalk. "In turn, CCL19 depended on polyp size, being significantly more abundant in medium and large than small polyps." (PMID 38338661, 2024). "Likewise, CCL19 association with polyp’s histological type could not be confirmed for CCL19 protein." (PMID 38338661, 2024). "Unpaired analysis on a larger set of samples confirmed lack of significant differences in CCL4 and CCL19 expression with respect to polyp size, both in lesions and normal mucosa." (PMID 38338661, 2024). "Specifically, CCL19 and CCL5 had reduced expression in polyp lesions." (PMID 21249124, 2011).
prostate tumor (2 papers, 2017 to 2019). "His study verifies that silencing of CCL19 reduces tumor cell proliferation and suppresses invasion and migration, suggesting that the CCL19/CCR7 axis may mediate the pathogenesis of human prostate tumor." (PMID 30430424, 2019).
renal carcinoma (2 papers, 2021 to 2022). A carcinoma arising from the epithelium of the renal parenchyma or the renal pelvis. "In addition, CCL19 also participates in the oncogenesis and progression of renal cancer." (PMID 35222545, 2022).
triple-negative breast carcinoma (2 papers, 2024 to 2026). An invasive breast carcinoma which is negative for expression of estrogen receptor (ER), progesterone receptor (PR), and human epidermal growth factor receptor 2 (HER2). "A unique functional subset of CCL19-expressing dendritic cells has been identified, showing favorable responses to anti-PD-1 therapy and displaying migratory and immunomodulatory phenotypes in triple-negative breast cancer." (PMID 41596347, 2026).
type 2 diabetes (2 papers, 2022 to 2024). "Furthermore, previous studies found that CCL19 is upregulated in inflamed islets in nonobese diabetic mice and type 2 diabetes, suggesting that CCL19 is widely upregulated in both type 1 and 2 diabetes." (PMID 35222545, 2022).
vitamin D deficiency (2 papers, 2013 to 2023). A nutritional condition produced by a deficiency of VITAMIN D in the diet, insufficient production of vitamin D in the skin, inadequate absorption of vitamin D from the diet, or abnormal conversion of vitamin D to its bioactive metabolites. "Thus vitamin D deficiency differentially affects the expression of CCL19 mRNA by ADLN DC in male and female mice." (PMID 23826346, 2013).
abscesses (1 paper, 2024). "In addition, CXCL13+ FBs expressed multiple other chemokines (i.e., CXCL12, CCL19), which likely further contribute to the spatial localization of the B cell population at the periphery of actively inflamed abscesses and sinus tracts." (PMID 38051587, 2024).
aortic valve calcification (1 paper, 2022). "Single-cell sequencing analysis and immunohistochemical staining of human aortic valve tissue samples showed that SCG2 and CCL19 were increased in Calcific aortic valve disease (CAVD) valves." (PMID 36589450, 2022).
Arterial thrombosis (1 paper, 2022). The formation of a blood clot inside an artery. "The baseline levels of IL-6, IL-10, VCAM-1, CCL19, BCA-1, IL-4, E-selectin, fractalkine, CXCL12, and GCP2 were found to differ statistically among the control, arterial thrombosis, AF-related venous thrombosis, and major bleeding groups (p < 0.05)." (PMID 36211709, 2022).
Atherosclerotic lesion (1 paper, 2022). A lesion associated with atherosclerosis, a multifactorial and multipart progressive disease manifested by the focal development within the arterial wall of lesions, that ranges from the development of a fatty streak, plaque progression, and plaque disruption. "Further, while the levels of CCL19 and CCL21 in the plasma in atherosclerotic lesions have been noticed, both these molecules are reported to be upregulated in carotid AS." (PMID 36187128, 2022).
atrophic gastritis (1 paper, 2020). "In an atrophic gastritis environment, the expression of CXCL14, CCL4, CCL26, CCL21, CCL2, CCL19, and CCL13 was correlated with the infiltration of central memory CD4 T cell." (PMID 33426088, 2020). "In extensive atrophic gastritis, the expression of CCL2 and CCL19 was correlated with the infiltration of central memory CD4 T cell, and CD56dim natural killer cell was associated with IL33 expression." (PMID 33426088, 2020).
Bell's palsy (1 paper, 2025). Partial or complete paralysis of the facial muscles of one side of a person's face. "(Genetic correlation between CCL19 and Bell’s palsy: 0.2105, p = 0.042; genetic correlation between VCAM1 and Bell’s palsy: 0.2478, p = 0.017; genetic correlation between OSM and Bell’s palsy: 0.41934, p = 0.021)." (PMID 40299566, 2025). "LDSC identified significant genetic associations between CCL19, VCAM1, OSM, and Bell’s palsy." (PMID 40299566, 2025). "Thus, CCL19, SELL and VCAM-1 may not be sequential activation of a single pathway, but rather synergize through different mechanisms such as chemotaxis, adhesion and barrier modulation to drive the inflammatory response and pathological injury in Bell’s palsy." (PMID 40299566, 2025).
Chagas disease (1 paper, 2017). A parasitic infection caused by Trypanosoma cruzi. "Some of these differentially expressed genes were previously associated to Chagas disease (eg, IL7, CCR7, CCL19, GATA4, HLA-DPB1)." (PMID 28575239, 2017).
chronic hepatitis B (1 paper, 2021). "We also examined how CCL19 influences HBV clearance and modulates HBV-responsive T cells in a mouse model of chronic hepatitis B (CHB)." (PMID 34218330, 2021).
chronic hepatitis C (1 paper, 2023). "Neo-lymphoid follicles expressing CCL19 and CCL21 are encountered in chronic inflammatory liver diseases, such as PBC, PSC and chronic hepatitis C." (PMID 37108648, 2023).
chronic obstructive pulmonary disease (1 paper, 2019). A chronic and progressive lung disorder characterized by the loss of elasticity of the bronchial tree and the air sacs, destruction of the air sacs wall, thickening of the bronchial wall, and mucous accumulation in the bronchial tree. "CXCL13 and CCL19 have been shown to be controlled by LT-dependent mechanisms in a smoke-exposed chronic obstructive pulmonary disease (COPD) model." (PMID 30972065, 2019).
Cirrhosis (1 paper, 2019). A chronic disorder of the liver in which liver tissue becomes scarred and is partially replaced by regenerative nodules and fibrotic tissue resulting in loss of liver function. "The results revealed the significant diagnostic values of PF4 and PPBP in cirrhotic HCC, and CCL19, CCL25 in non-cirrhotic HCC, while no significant diagnostic values of CNR1 in HCC with or without cirrhosis were found." (PMID 31346321, 2019).
Cognitive impairment (1 paper, 2025). Abnormal cognition is characterized by deficits in thinking, reasoning, or remembering. "Cxcl13, Ccl2 and Ccl19 are 3 pro-inflammatory chemokines previously associated with cognitive impairments and that are also upregulated in AD, Ccl19 being a peripheral biomarker." (PMID 41216177, 2025).
colorectal tumor (1 paper, 2022). "Murine colorectal tumor cell lines (CT26 and MC38) stably overexpressing mouse C-C motif chemokine ligand 3 (CCL3), CCL19, CCL21, and X-C motif chemokine ligand 1 (XCL1) were established by lentiviral transduction." (PMID 36654820, 2022).
cutaneous leishmaniasis (1 paper, 2012). Leishmaniasis affecting the skin. "In cutaneous leishmaniasis, a number of chemokines were shown to be expressed in Humans, of which CCL2, CCL19 and CCL17." (PMID 22457760, 2012).
dacryoadenitis (1 paper, 2018). Inflammation and enlargement of the lacrimal gland. "Thus, type I IFN signaling contributed to the male-specific upregulation of disease-relevant genes (Cxcl9, Ccl19, Epsti1) and was required for dacryoadenitis development in male NOD mice." (PMID 30347820, 2018). "We found that upregulation of Cxcl9, Ccl19 and Epsti1 was altered in NOD mice deficient in type I IFN signaling and these mice also failed to develop dacryoadenitis." (PMID 30347820, 2018). "While Treg-depletion was not sufficient to drive dacryoadenitis in castrated male NOD mice, chemokines (Cxcl9, Ccl19) and other potentially disease-relevant genes (Epsti1, Ubd) were upregulated in male lacrimal glands." (PMID 30347820, 2018).
emphysema (1 paper, 2022). "Emphysema patients, but not subjects with bronchiolitis, were associated with enhanced B-cell homing and activation pathways and the expression of genes such as CXCL13, CCL19 and POU2AF1 correlated with emphysema severity." (PMID 35820851, 2022).
fibromyalgia (1 paper, 2022). A chronic disorder of unknown etiology characterized by pain, stiffness, and tenderness in the muscles of neck, shoulders, back, hips, arms, and legs. "The top five proteins that distinguished fibromyalgia patients from plasma controls were in serum STAMBP, SIRT2, CD40, AXIN1 and IL-7 and in CSF (CCL19, CCL23, IL-18, CX3CL1, FGF19, CXCL10, CCL11)." (PMID 36327322, 2022).
HCMV infection (1 paper, 2017). "Thus, HCMV is able to not only inhibit upregulation of the respective chemokine receptor CCR7, when infecting iDCs prior to maturation, but also hamper migration toward CCL19 beyond CCR7-targeting, via the induction of adhesion upon HCMV infection of mDCs." (PMID 28484459, 2017). "Treatment with Mg/EGTA strongly reduced spontaneous and CCL19-directed chemotaxis comparable to the reduction observed for HCMV-positive mDCs, while additional HCMV infection did not further reduce CCL19 transwell migration." (PMID 28484459, 2017).
head and neck cancer (1 paper, 2022). A primary or metastatic malignant neoplasm affecting the head and neck. "In head and neck cancers, CCL19/CCR7 activation produced phosphorylation of mTOR that elevated cell survival." (PMID 35203305, 2022).
hearing loss (1 paper, 2024). "This study identified CCL19 as a common risk factor for various types of hearing loss through MR analysis, highlighting the crucial role of inflammatory proteins in hearing loss." (PMID 39677857, 2024). "Although this study emphasizes the key role of CCL19 in hearing loss, current research findings suggest that further investigation of the CCL family, especially CCL2, is necessary." (PMID 39677857, 2024). "Experimental studies have demonstrated that noise exposure significantly elevates CCL19 expression in GRAIL wild-type mice, whereas GRAIL gene deletion reduces CCL19 levels and subsequently attenuates hearing loss, suggesting CCL19 as a promising therapeutic target for noise-induced hearing loss." (PMID 39677857, 2024). "Accumulating evidence strongly supports CCL19’s role as a risk factor in hearing loss development." (PMID 39677857, 2024). "This study investigated the causal relationships between various inflammatory proteins (including CCL19, CDCP1, and TSLP) and multiple types of hearing loss (SNHL, SIHL, and OHL)." (PMID 39677857, 2024).
hypercoagulable (1 paper, 2020). "As a soluble chemokine released during platelet activation and a sensitive marker of blood hypercoagulable state, CCL19 also induce monocytes to gather to the lesion site and play an important role in promoting inflammatory response." (PMID 33424012, 2020).
hyperplastic polyp (1 paper, 2024). A polyp found mainly in the stomach and colon. "However, CCL4 (p = 0.052) and CCL19 (p = 0.088) expression in lesions tended to be lower in hyperplastic polyps." (PMID 38338661, 2024).
Hypertension (1 paper, 2011). The presence of chronic increased pressure in the systemic arterial system. "We have demonstrated recently that Ccl19 (aFD = 1.7) and Hcrt (aFD = 2.1) are differentially expressed in BPH/2J mice in early and established phases of hypertension." (PMID 21541337, 2011).
idiopathic interstitial pneumonia (1 paper, 2024). A class of diffuse lung diseases that typically affect the pulmonary interstitium, although some also have a component affecting the airways (for instance, Cryptogenic organizing pneumonitis). "In lung samples of idiopathic interstitial pneumonia, CCL19 is elevated, and CCR7 protein was expressed in interstitial areas restricted to blood vessels and mononuclear cells." (PMID 39768150, 2024).
inclusion body myositis (1 paper, 2019). A slowly progressive degenerative inflammatory disorder of skeletal muscles characterized by late onset weakness of specific muscles and distinctive histopathological features. "It has been reported that the CCL19/CCR7 chemokine system is expressed in inflamed muscles of polymyositis and inclusion body myositis (IBM) and may be involved in the pathogenesis of polymyositis and IBM." (PMID 31068931, 2019).
intrahepatic cholangiocarcinoma (1 paper, 2022). A carcinoma that arises from the intrahepatic bile duct epithelium in any site of the intrahepatic biliary tree. "In intrahepatic cholangiocarcinoma, FTO inhibited angiogenesis and tumor cell migration via upregulating C-C motif chemokine ligand 19 (CCL19) expression." (PMID 36291060, 2022).
keloid (1 paper, 2024). An irregularly shaped, elevated mark on the skin caused by deposits of excessive amounts of collagen during wound healing. "Following the pseudotime of fibroblasts from Fs0 to Fs1 or from normal scars to keloids, the gene expression levels of APCDD1 (a papillary dermal fibroblast marker) and CCL19 (a pro-inflammatory marker) were observed in the beginning and were seen to decrease gradually thereafter." (PMID 38254097, 2024).
laryngeal squamous cell carcinoma (1 paper, 2025). A squamous cell carcinoma that arises from the larynx. "A study on laryngeal squamous cell carcinoma has shown that chemokine receptors CCR6/CCR7 and their ligands CCL19/CCL20 synergically drive cervical lymph node metastasis of laryngeal squamous cell carcinoma through differential expression and Treg recruitment." (PMID 41445742, 2025).
MALT lymphoma (1 paper, 2021). An indolent, extranodal type of non-Hodgkin lymphoma composed of small B-lymphocytes (centrocyte-like cells). "In addition, several molecules such as CXCL13, CCL18, CCL19, CCL 20 and TLR 10 were found to be dysregulated in MALT lymphoma, suggesting that not only modulate H. pylori infection but also affect the risk of MALT lymphoma." (PMID 35008340, 2021).
mastitis (1 paper, 2022). Inflammation of breast tissue during lactation or postpartum due to an obstructed duct or infection. "In the case of the cytokine–cytokine-receptor interaction pathway, other genes, such as CD40, IL1RN, CXCR1, TNFRSF6B, and CCL19, were found to be involved in mastitis defense or immune response, as all these genes were upregulated in the mastitic cows based on their FC values." (PMID 35723402, 2022).
mastocytoma (1 paper, 2022). A localized tumor composed of sheets of mast cells without atypia. "IL-7– and CCL19-expressing (7 × 19) CAR T cells showed a stronger therapeutic effect against mouse mastocytoma with increased endogenous DC and T-cell infiltration." (PMID 36059449, 2022).
mesothelioma (1 paper, 2025). A usually malignant and aggressive neoplasm of the mesothelium which is often associated with exposure to asbestos. "Taken together, our findings suggest that ICB is most effective in inflamed mesotheliomas harbouring high IL24/CCL19 expression, TLSs and low EMT." (PMID 40691143, 2025). "B-lymphocyte infiltration inferred by transcriptome deconvolution, was correlated with both IL24 and CCL19 and the ratio of IL24 to EMT was significantly higher in R- vs NR- mesotheliomas and was associated for response with an AUROC of 0.889, p = 0.001." (PMID 40691143, 2025). "Significantly higher levels of multiple chemokines were expressed in R- vs NR- mesotheliomas, namely CCL5, CCL16, CCL17, CCL19, CCL21, CCL25, and CXCL14 Benajmini-Hochberg adjusted P values < 0.05." (PMID 40691143, 2025).
nephritis (1 paper, 2023). Inflammation of renal tissue. "Consistently, our in vivo data showed that the expression levels of CCL2, CCL3, CCL4, CCL5, CCL19, and CXCL10 increased in the kidney of MRL.Faslpr mice during the development of nephritis." (PMID 37567910, 2023).
oral cancer (1 paper, 2024). "We further examined the expression of CCR4, CXCR3, P2RY14, CCR2, CCR8, and CCL19 in highly aggressive oral cancer cell lines and tissues." (PMID 38213736, 2024). "The expression of CCR4, CXCR3, CCR2, and CCR8 was higher in highly invasive oral cancer cell lines (SCC-25, CAL-27, and FaDu) than in the less aggressive cell line (HSC-2), whereas CCL19 and P2RY14 expression showed the opposite trend." (PMID 38213736, 2024). "Further analysis of gene expression in clinical tissues revealed that CCR4, CXCR3, CCR2, and CCR8 exhibited higher expression in oral cancer cells of patients with metastasis compared to those without, whereas CCL19 and P2RY14 displayed the opposite trend." (PMID 38213736, 2024).
Pain (1 paper, 2023). An unpleasant sensory and emotional experience associated with actual or potential tissue damage, or described in terms of such damage. "Among these factors, the chemokine (C-C motif) ligand 19 (CCL19) is a known mediator of synovial inflammation and is involved in orofacial neuropathic pain." (PMID 37569811, 2023).
pancreatic adenocarcinoma (1 paper, 2022). "Stimulation of the CCR7-expressing pancreatic adenocarcinoma-derived cell line, PANC1, with CCL19 led to enhanced expression of p-ERK, p-AKT, N-cadherin and MMP-9, markers of EMT progression, further implicating CCR7 in the metastatic progression of pancreatic adenocarcinomas." (PMID 35203305, 2022).
papillary renal cell carcinoma (1 paper, 2022). A rare subtype of renal cell carcinoma, arising from the renal tubular epithelium and showing a papillary growth pattern, which typically manifests with hematuria, flank pain, palpable abdominal mass or nonspecific symptoms, such as fatigue, weight loss or fever. "CCL19 is a critical component of an immune-related prognostic classifier for the prognostic evaluation of patients with papillary renal cell carcinoma." (PMID 35222545, 2022).
pemphigus (1 paper, 2022). Pemphigus is a group of rare autoimmune diseases that cause blistering of the skin and mucous membranes (mouth, nose, throat, eyes, and genitals).This conditioncan occur at any age, but often strikes people in middle or older age. "Notably, CCL19, CCL26, CCL27 and CXCR5 were highly expressed chemokines and chemokine receptors detected in pemphigus group." (PMID 35449056, 2022).
proliferative vitreoretinopathy (1 paper, 2019). Vitreoretinal membrane shrinkage or contraction secondary to the proliferation of primarily retinal pigment epithelial cells and glial cells, particularly fibrous astrocytes, followed by membrane formation. "The comparison of cytokine profiles in different stages of proliferative vitreoretinopathy (PVR) in primary retinal detachment (pRD) identified the chemokine (C-C motif) ligand 19 (CCL19) as specifically upregulated in early PVR (C1)." (PMID 30943234, 2019).